IL6 (interleukin 6)
Diseases named in the same sentence as IL6 in open-access papers (continued):
Sharing a sentence is not in itself a finding about the gene and the disease.
Sepsis (continued). "Salidroside reduced the production of pro-inflammatory cytokines (TNF-α and IL-6) through a SIRT1-mediated inhibition of NF-κB activation pathway in the early sepsis phase." (PMID 28931916, 2017). "Accordingly, the severity of the model presented here, in combination with the high expression of IL-6 at 24 h measured before oxygen intervention, indicates this study applies to a severe state of sepsis." (PMID 29204105, 2017). "Pro-inflammatory cytokines including tumor necrosis factor α (TNFα), IL-1β, IL-6, and IL-8 are potent immune mediators that exacerbate multiple equine diseases such as sepsis and laminitis." (PMID 29034249, 2017). "In parallel with these forebrain cholinergic alterations, microglial activation (in the cortex) and increased Il1b and Il6 gene expression (in the cortex), and Il1b gene expression (in the hippocampus) were observed in mouse sepsis survivors." (PMID 29326685, 2017). "Plasma interleukin-6 levels increased during unresuscitated sepsis and decreased during resusciation in both groups, but they were lower at study end in the Lac ≥10% group (p = 0.047)." (PMID 28499395, 2017). "Accumulating evidence demonstrates that the inhibition or specific antagonism of MCP-1 results in decreased release of TNF-α, IL-1β and IL-6 by macrophages and confers survival benefits on mice following sepsis." (PMID 28472164, 2017). "Elevated levels of cytokines, such as IL-1β, TNF-α, and IL-6, have been observed in the brain parenchyma and cerebrospinal fluid after sepsis." (PMID 28236057, 2017). "In our study, levels of the pro-inflammatory mediator IL-6 decreased in the groups receiving tadalafil compared to the untreated sepsis group." (PMID 27622284, 2017). "In the present study, TNFα, IL-1β and IL-6 transcript levels were all increased in gastrocnemius and diaphragm muscles during sepsis, but this response was significantly greater and more sustained over time in the diaphragm muscle." (PMID 28883493, 2017). "It was identified that initial neonatal sepsis onset (within the first 24 hours of infection) was best diagnosed with a combination of IL-6 and CRP detection, with a cutoff of 18 pg/mL for IL-6 and 10 pg/mL for CRP (sensitivity: 89%; specificity: 73%)." (PMID 28487810, 2017). "IL-6 is of special interest, due to its potential ability to both diagnose neonatal sepsis and predict mortality due to the condition, as well as its relatively uniform range in cutoffs across these preliminary studies." (PMID 28487810, 2017). "CORM administration was able to inhibit sepsis-induced NF-κB activation in lung and liver and reduced serum cytokine levels of IL-6 and TNF-α." (PMID 28655348, 2017). "A marked increase of TNF-α and IL-6 secretion was observed in the CLP sepsis group compared with the sham group (p < 0.05)." (PMID 28694565, 2017). "In our study, filgrastim administration apparently upregulates the systemic release of IL-8, IL-6, and IL-10 on the first day of fever, with little impact on sepsis discrimination capability." (PMID 28769538, 2017). "The induction of sepsis-associated blood C-reactive protein (CRP) and the pro-inflammatory cytokine IL-6 in response to MRSA infection was also suppressed in pigs that received Epi-1." (PMID 28177877, 2017). "As pro-inflammatory cytokines, serum and plasma TNF-α and IL-6 levels have been shown to increase significantly among patients with sepsis, particularly in those who are culture-positive." (PMID 29073262, 2017). "Here the authors show that TLR4 signaling in these cells requires Fcα/μR (CD351) and that they are a major source of IL-6 in a mouse model of sepsis." (PMID 27146354, 2016). "Combined, these results indicate that the severity of sepsis, as deduced from the levels of IL-6, and the time of initiation as well as the maintenance treatment of anti-cytokine strategies will play a pivotal role in the therapeutic outcome." (PMID 27044016, 2016).
Sepsis (continued). "Sepsis was indicated by increased body temperature (onset at 30 h PI), bacteraemia, and neutrophilia, together with increased IL-6, CRP, SAA, and decreased iron." (PMID 26879530, 2016). "Plasma samples from sepsis patients, in contrast, induced variable levels of endothelial activation despite their comparable levels of IL-6 and TNF-α." (PMID 27503310, 2016). "The IL-6 values for the PT group were 8.39 ± 12.74 pg/mL, 866.64 ± 1233.11 pg/mL, and 17.6 ± 35.40 pg/mL at presepsis, sepsis, and postsepsis, respectively (P = 0.003, Friedman test)." (PMID 27293317, 2016). "The proinflammatory cytokines IFN-γ, TNF-α, and IL-6 were elevated in 9/11 PT infants with sepsis but only in 1/12 VPT infants with sepsis (P < 0.05, χ2 test), resulting in 10/23 infants with sepsis identified." (PMID 27293317, 2016). "Regarding TNFα, IL-6, IL-10, sTNFr, our results confirm that both pro-inflammatory and anti- inflammatory responses occur early and simultaneously in human sepsis as well as after mild CLP procedure in mice." (PMID 27574993, 2016). "Our results therefore suggest that IL-6 plays a major role in the initiation of sepsis-related alterations in GI motility, permeability and inflammation, but loses its potency partially once sepsis-induced alterations are full-blown." (PMID 27044016, 2016). "More recently, a panel of biomarkers of lung epithelial injury and inflammation (SP-D, sRAGE, IL-8, CC16, and IL-6) provided excellent discrimination for diagnosis of ARDS in patients with severe sepsis." (PMID 26980924, 2016). "A major proinflammatory cytokine that plays a pivotal role in the pathogenesis of sepsis is interleukin-6 (IL-6)." (PMID 27044016, 2016). "Pro-inflammatory cytokines like TNF-α, IL-1β, and IL-6 are responsible for severe manifestations in sepsis and septic shock." (PMID 27430881, 2016). "Patients with sepsis exhibit high level of circulating pro-inflammatory cytokines such as tumor necrosis factor (TNFα) or Interleukin-6 and IL-6 seems to correlate strongly with decreased survival in septic patients." (PMID 27574993, 2016). "IL-6 is a potent inducer of the hepatic acute phase response observed in many systemic inflammatory responses (i.e., sepsis)." (PMID 26942201, 2016). "And some reports indicated that NF-κb pathway was activated during sepsis and increased expression of proinflammatory cytokines such as IL-6, IL-1β, and TNF-α, leading to excessive inflammation response." (PMID 28042205, 2016). "This suggested that citrulline supplementation reduced the release of TNF-α, IL-6, and IL-1β in the early stages of sepsis." (PMID 27195281, 2016). "CLP-induced sepsis significantly impaired GI motility, as reflected by a drop in %GE and GC; repeated treatment with anti-IL-6 antibodies significantly increased the GC, whilst the effect on %GE was not statistically different." (PMID 27044016, 2016). "Inflammatory cytokines (TNF-α, HMGB1, IL-1β, IL-6, and IL-8) were increased while anti-inflammatory cytokines (IL-10) were decreased, in serum and lung in sepsis patients." (PMID 27413421, 2016). "Plasma levels of TNF-α, IL-6, and IL-10 were strongly increased after 3 and 6 hours from LPS administration, as well as after sepsis induction in the CLP model, in comparison to those measured in saline-injected or sham-operated mice." (PMID 26963510, 2016). "In this scenario, miRNA at the same time regulate the expression of sepsis related genes, such as IL-6 and TNF, and are regulated in their own expression by these factors, highlighting the deep integration of miRNAs in the pathophysiology of septic disease." (PMID 26761003, 2016). "Our model of sepsis displays early and massive inflammation as TNFα and IL-6 rise significantly (60-fold higher concentration as compared to Sham for both these cytokines at the second hour post CLP)." (PMID 27574993, 2016). "Surprisingly, induction of IL-6, the main cytokine responsible for hepatic STAT3 activation during sepsis, was reduced in TR deficient mice." (PMID 27484112, 2016).
Sepsis (continued). "Together, these results indicated the critical role of MZ B cells and IL-6 for the exacerbation of sepsis induced by E. coli injection and CLP." (PMID 27146354, 2016). "PC2iNTS is characterized by a cytokine profile typically described in patients with sepsis, with concomitantly raised proinflammatory (IL-6, IL-8, CXCL10, and IL-15) and anti-inflammatory (IL-10 and IL-1Ra) cytokines." (PMID 27170644, 2016). "However, since pathological conditions other than sepsis (trauma, burn injury, etc.)may be associated with elevated IL-6 and/or CRP levels, the authors themselves warn about the need to rule out such conditions upon interpreting postmortem values of IL-6 and CRP." (PMID 27239102, 2016). "Both IL-8 and IL-6 are strongly associated with mortality, AKI, and ARDS in observational studies of sepsis." (PMID 27431667, 2016). "Pentoxifylline, a xanthine-derived phosphodiesterase inhibitor that decreases TNF-α and IL-6 production, has been reported to improve the clinical outcome of preterm sepsis." (PMID 28066425, 2016). "An early study demonstrated a strong correlation between the serum level of IL-6 and the degree of hypothermia in sepsis." (PMID 27177150, 2016). "During the early hyper-inflammatory phase of sepsis, specific depletion of Foxp3+ Tregs leads to a more severe course of sepsis with a higher mortality rate and a significantly higher IL-6 level." (PMID 27941849, 2016). "Increased systemic and local levels of IL-1 β and IL-6, together with tumor necrosis factor alpha, are known to correlate with a more severe development of sepsis in mice." (PMID 27527222, 2016). "Citrulline supplementation reduced the release of TNF-α, IL-6, and IL-1β in the early stages of sepsis." (PMID 27195281, 2016). "Some researchers have tried to improve the prognostic accuracy of MEDS by combining it with sepsis biomarkers such as C-reactive protein, procalcitonin, and interleukin-6, with encouraging results." (PMID 27077648, 2016). "Another study showed that Presepsin was better than IL6, CRP and PCT in assessing the risk of death within 30 days after onset of sepsis." (PMID 27389015, 2016). "It has been repeatedly suggested that the optimal choice of dosage and time of administration of anti-IL-6 is pivotal in order to obtain beneficial effects during sepsis." (PMID 27044016, 2016). "Few differences according to HIV status were observed, but one of these studies reported higher plasma IL-10 in the presence of unaltered IL-6 among HIV-positive patients with sepsis." (PMID 27719675, 2016). "IL-6 is the most well-established early biomarker of sepsis severity in the murine CLP model, as early levels of IL-6 in the serum are highly predictive of later mortality." (PMID 26790027, 2016). "Another investigation found that a blockade of the α2A-adrenoceptor with BRL-44408 suppresses early pro-inflammatory mediators (TNF-α, IL-6, etc.)and, thus, improves liver dysfunction during sepsis." (PMID 27347929, 2016). "An analysis for severe sepsis/septic shock/SIRS in CAP/pneumococcal disease was available only for the SNPs IL6 rs1800795 and IL10 rs1800896 with both series providing significant results." (PMID 27725770, 2016). "Because of the highly inflammatory nature of canine babesiosis, increased concentrations of the pro-inflammatory cytokine IL-6 would be expected as has been described in humans and dogs with sepsis, as well as dogs with piroplasmoses." (PMID 26953797, 2016). "Inflammatory cytokines, such as TNFα and interleukin-6 (IL-6), are key mediators not only of sepsis but also of PCAS." (PMID 27612461, 2016). "IL-6 is a marker of sepsis severity, with elevated levels of this cytokine during early sepsis correlating with increased mortality rates in both humans and mice (69, –, 71)." (PMID 27303721, 2016).
Sepsis (continued). "Plasma samples from sepsis patients differed substantially in their potential to induce endothelial activation and monocyte adhesion despite their almost identical interleukin-6 and tumor necrosis factor-alpha levels." (PMID 27503310, 2016). "It is well known that viral and bacterial infections contribute to the pathogenesis of severe sepsis, which is characterized by an overwhelming production of NO and proinflammatory cytokines, such as IL-6." (PMID 27049378, 2016). "As for the other inoculated pigs, sepsis was indicated by increased body temperature (onset at 15 and 22 h, respectively), bacteraemia, and neutrophilia, together with increased IL-6, CRP, SAA, and decreased serum iron." (PMID 26879530, 2016). "High plasma IL-6 helps in detecting severe sepsis in admitted patients with the suspicion of infection." (PMID 27861595, 2016). "In the caecal ligation and puncture animal model of sepsis, we demonstrated that systemic and colonic interleukin-6 levels are significantly increased coinciding with an impaired colonic barrier function." (PMID 27044016, 2016). "IL-6 is elevated in the serum of sepsis patients, and IL-6 levels correlate with the severity of septic shock." (PMID 26761003, 2016). "The proinflammatory cytokines (TNF-α, IFN-γ, and IL-6) increase differentially in neonates with sepsis based on gestational age." (PMID 27293317, 2016). "Following CLP-induced sepsis, we detected a significant rise in the serum levels of proinflammatory cytokines such as IL-6 and TNF-α, as well as a simultaneous increase in the serum levels of the anti-inflammatory IL-10." (PMID 27044016, 2016). "IL-6 can be released into the circulation following various pathological events such as physical exercise, trauma, sepsis, and thermal injury." (PMID 27524970, 2016). "The hypocalcemia of critically ill patients with burn injury or sepsis is associated with CASR gene upregulation by TNF-alpha and IL-1beta via kappaB elements, and by IL-6 via Stat1/3 and Sp1/3 elements in the CASR gene promoters, respectively." (PMID 27679579, 2016). "TNF-α is widely accepted as the initial mediators in the pathogenesis of sepsis; it plays a key role in endogenous inflammation to induce IL-1β and IL-6 production during the early phase of CLP." (PMID 26273145, 2015). "Circulating levels of IL-6, IL-8, sTNFR-1, Ang-2, and sVCAM-1 were higher in those with sepsis compared to sterile inflammation." (PMID 26492036, 2015). "In fact, respiratory chain enzymes were always similarly inhibited although the severity of disease and inflammatory response (circulating interleukin-6 levels) were apparently lower during sepsis than during cardiogenic shock." (PMID 25757508, 2015). "In contrast to ALI-sepsis-induced multi-organ increase in Ngal as well as nuclear factor-kappa-B (NF-κB)-responsive genes, including Tnf, Mcp-1, IL-6, and Cox2, the angiogenic gene expression decreased in the lung, kidney, and liver." (PMID 25959381, 2015). "The data obtained from septic patients confirm results from animal models presenting a correlation of plasma-NGAL with IL-6 during sepsis." (PMID 25893429, 2015). "So far, human trials and animal experiments have demonstrated that the generation of inflammatory cytokines, including TNF-α and IL-6, is one of the important characteristics of sepsis, and excessive inflammatory response can lead to acute lung injury." (PMID 25929655, 2015). "In pediatric patients with sepsis, a cytokine storm occurred with an increase of sIL-2R, IL-6, IL-8, and TNF-α." (PMID 26315105, 2015). "The phylum Firmicutes and the families Streptococcaceae and Lactobacillaceae were negatively correlated with many inflammatory markers of sepsis progression, such as IL-6, IL-18, HMGB1 and CRP." (PMID 25881250, 2015). "MT-2 up-regulated Akt phosphorylation and abrogated the increase of IL-1β and IL-6 mRNA expression from macrophages that stimulated with burn sepsis serum." (PMID 26550025, 2015).
Sepsis (continued). "It is not always difficult to decide the induction of the bundle care recommended by the Surviving Sepsis Campaign, as most cases exhibit significant increases in the plasma levels of the inflammatory biomarkers such as IL-6 and PCT." (PMID 26161427, 2015). "It was demonstrated that interleukin-6 (IL-6) and interleukin-1 receptor antagonist were already increased 1–2 days before the clinical diagnosis of sepsis." (PMID 25894336, 2015). "When IL-6 was detected, it was at considerably lower levels than in other conditions where hepcidin is notably induced: IL-6 was typically one or more orders of magnitude higher during uncomplicated malaria, sepsis, or experimental endotoxemia." (PMID 26394303, 2015). "While IL6 was previously identified as biomarker for sepsis, GADD45B, SOCS3, and IRG1 were shown to be up-regulated in septic patients." (PMID 25814982, 2015). "Mediators of acute inflammation such as IL-6, IL-8, and TNFR-1 have long been implicated in the pathophysiology of SIRS/Sepsis." (PMID 26492036, 2015). "A significant decrease (P = 0.002) of IL-6 was found between sepsis (650 ± 989 pg/ml) and bacteremia (39.63 ± 58.58 pg/ml), as well as between sepsis and viremia (17.47 ± 22.40 pg/ml; P = 0.002)." (PMID 26315105, 2015). "To evaluate the degree of onset of systemic inflammation in mice with S. aureus-induced pneumonia, we measured the level of IL-1β and IL-6 in blood as the representative cytokines for systemic induction of sepsis." (PMID 26333035, 2015). "We found high circulating plasma cytokine levels, which in comparison to their baselines values showed peaks immediately after sepsis/VILI induction (TNF-α) or three hours following induction (IL-6)." (PMID 25879802, 2015). "Some antioxidants such as MitoQ, MitoE, and melatonin can reduce IL-1β and IL-6 levels and decrease NFκB activation, effect observed in a rat model with acute LPS sepsis." (PMID 26457108, 2015). "In Gram-negative sepsis IL-6 and TNF-α showed the best AUC values (both 0.93); in Gram-positive sepsis the best AUC was found for IL-6 (0.91); in yeast sepsis IL-6, IL-8, and IL-10 showed the highest AUC values (0.92 for all)." (PMID 26635427, 2015). "Our present study shows that delayed administration of human kallistatin markedly attenuated kidney, liver and lung injury in association with reduced serum levels of TNF-α, IL-6 and/or HMGB1 in mice with established sepsis." (PMID 25930108, 2015). "Interleukin-6 was higher in patients with sepsis (187 (86 to 615) pg/ml; n = 15; P <0.05) or cardiogenic shock (387 (43 to 626) pg/ml; n = 15; P <0.05) than in controls (4 (1 to 15) pg/ml; n = 10)." (PMID 25757508, 2015). "Our results indicated that the expression of CX3CL1, IL-6R, TNF-a, IL-1ß and IL-6 were significantly higher in the sepsis patients (subtype) than in the healthy controls." (PMID 25888255, 2015). "It has been reported that DM (12.5 mg/kg, i.p.)inhibits inflammatory mediators, including cytokines (TNF-α, IL-1β and IL-6) and chemokines in sepsis mice model." (PMID 26391752, 2015). "Interleukin 6 (IL-6), a representative proinflammatory cytokine, has been reported as one of the most useful markers to determine the severity of sepsis." (PMID 26161427, 2015). "We found that the patients with sepsis expressed significantly higher IL-1ß and IL-6 levels than the healthy controls, as predicted." (PMID 25888255, 2015). "As expected, well established LPS-induced inflammatory pathways and typical markers for the onset of sepsis, such as IL-1, IL-6, TNFα, are also among the pathways with the most significant up regulation after LPS-challenge." (PMID 26197109, 2015). "The differences in the expression levels of ADAM10 substrates (CX3CL1, IL-6R and TNF-a) and the pro-inflammatory cytokines IL-1ß and IL-6 according to the ADAM10 genotype were analyzed in PBMCs from the sepsis patients and the controls." (PMID 25888255, 2015).